MAST3 (microtubule associated serine/threonine kinase 3)
Description:
Serine/threonine kinase that phosphorylates ARPP19 at 'Ser-62', resulting in protein phosphatase 2A (PP2A) inhibition by ARPP19.
Synonyms: KIAA0561; DEE108
Tractability: Small molecule: a high-quality ligand is known; it belongs to a druggable protein family. PROTAC: it is named in the literature on targeted protein degradation; ubiquitination databases record sites on it; its protein half-life has been measured; a small molecule that binds it is known.
Target class: Enzyme; AGC protein kinase group; Protein Kinase; Kinase; AGC protein kinase MAST family
Safety:
Unwanted effects reported when the protein is acted on. In parentheses: how it was acted on, where the effect was seen, and who reports it.
neutropenia (source: ClinPGx)
Gene: Protein-coding gene on chromosome 19 (18,097,749 to 18,151,692, forward strand). Ensembl gene ENSG00000099308.
Subcellular location: Cytoplasm
Subcellular location (Human Protein Atlas): Nuclear speckles
Gene Ontology:
Molecular function: protein binding; protein serine kinase activity; protein serine/threonine kinase activity; ATP binding; magnesium ion binding; protein kinase activity
Biological process: negative regulation of phosphatase activity; protein phosphorylation; cytoskeleton organization; intracellular signal transduction
Cellular component: cytoplasm; microtubule cytoskeleton
Genetic constraint (gnomAD): Loss-of-function variants: 36 observed, 101.99 expected, observed/expected ratio (o/e) 0.35, 90% interval 0.27 to 0.47. The upper end of that interval is the gene's LOEUF score, 0.47, which puts it in group 2 of 6, group 1 being the genes least tolerant of losing a copy. Missense variants: 1,258 observed, 1,651.6 expected, observed/expected ratio (o/e) 0.76, 90% interval 0.73 to 0.8. Synonymous variants: 713 observed, 700.5 expected, observed/expected ratio (o/e) 1.02, 90% interval 0.96 to 1.08.
Homologues: Orthologues: macaque MAST3 (97% identical), dog MAST3 (92% identical), chimpanzee MAST3 (91% identical), pig MAST3 (90% identical), rat Mast3 (90% identical), mouse Mast3 (88% identical), guinea pig MAST3 (88% identical), tropical clawed frog mast3 (74% identical), zebrafish mast3b (65% identical), zebrafish mast3a (59% identical), Drosophila melanogaster dop (46% identical), Caenorhabditis elegans kin-4 (41% identical), and 4 more. Paralogues in human: MAST2 (61% identical), MAST4 (61% identical), MAST1 (57% identical), LATS2 (16% identical), LATS1 (16% identical), DMPK (12% identical), SGK1 (12% identical), SGK3 (12% identical), STK32C (11% identical), MASTL (11% identical), STK32B (10% identical), SGK2 (10% identical), and 1 more.
Diseases named in the same sentence as MAST3 in open-access papers:
MAST3 is named in the same sentence as 21 diseases in open-access papers, as found by Europe PMC text mining. Sharing a sentence is not in itself a finding about the gene and the disease. The quoted sentences say what the papers report.
Obesity (4 papers, 2021 to 2024). Accumulation of substantial excess body fat. "Concordantly, MR analysis revealed that, as this site becomes methylated, the expression of MAST3 decreases (B = −0.2, p = 1.6 × 10−69) and the risk of obesity increases (B = −0.06, p = 6.9 × 10−14)." (PMID 34207686, 2021). "We found that the higher methylation at the cg02814054 site within MAST3 contributes to obesity by lowering the expression of this gene." (PMID 34207686, 2021). "Co-localization and subsequent MR analysis revealed that the cg02814054 methylation site within MAST3 contributes to obesity." (PMID 34207686, 2021).
and epileptic encephalopathy (2 papers, 2021 to 2025). "For example, mutations in Microtubule-associated serine/threonine-protein kinase 3 (MAST3) are implicated in developmental and epileptic encephalopathy (DEE108)." (PMID 41152984, 2025). "MAST3 may play a role in developmental and epileptic encephalopathies." (PMID 34835087, 2021).
inflammatory bowel disease (2 papers, 2022 to 2023). A spectrum of small and large bowel inflammatory diseases of unknown etiology. "A study described MAST3 as an inflammatory bowel disease (IBD, MIM: 601458) susceptibility gene that regulates NF-κB (MIM: 164011) activity through TLR481 (MIM: 603030)." (PMID 34993496, 2022). "A potential role for MAST3 in inflammatory bowel disease may be explained by the misregulation of the same pathway." (PMID 37569286, 2023). "MAST3 was found to be a factor in inflammatory bowel disease (IBD) tissues to increase Toll-like receptor (TLR) 4-dependent NF-κB activity and knock-down of MAST3 resulted in reduced NF-κB activity." (PMID 37569286, 2023).
mastitis (2 papers, 2018 to 2023). Inflammation of breast tissue during lactation or postpartum due to an obstructed duct or infection. "As a result, the genes MARCH3, MAST3, and PDGFD were proposed as potential causative factors for mastitis susceptibility." (PMID 36669036, 2023). "The SNP rs41255569 on BTA7, an upstream gene variant and in significant association with susceptibility to mastitis in parity 3, is mapped very near to a functionally known candidate genes MAST3 (microtubule associated serine/threonine kinase 3) and IFI30 (lysosomal thiol reductase)." (PMID 29755506, 2018). "Genes involved in lymphocyte developments (e.g., MAST3 and STAB2) and genes involved in macrophage recruitment and regulation of inflammations (PDGFD and PTX3) were suggested as possible causal genes for susceptibility to – and recoverability from mastitis, respectively." (PMID 29755506, 2018).
Abdominal obesity (1 paper, 2025). Excessive fat around the stomach and abdomen. "MAST3 may be better described as an abdominal obesity–affecting gene, suggesting that estimation of liver fat may have been driven by abdominal obesity predictors in the algorithm." (PMID 40166930, 2025).
epilepsy (1 paper, 2021). A brain disorder characterized by episodes of abnormally increased neuronal discharge resulting in transient episodes of sensory or motor neurological dysfunction, or psychic dysfunction. "The variants of DUF domain contributed to NDD with a core ASD phenotype while variants of STK contributed to NDD with a core epilepsy phenotype, therefore, conducive to future genetic counseling of MAST3." (PMID 35095415, 2021). "Together with bioinformatic analyses and functional studies on zebrafish model, our study indicated that MAST3 variants may be related to variable neurodevelopmental phenotypes from intellectual disability (ID) with epilepsy to ID with autistic spectrum disorder (ASD)." (PMID 35095415, 2021).
Huntington disease (1 paper, 2022). Huntington disease (HD) is a rare neurodegenerative disorder of the central nervous system characterized by unwanted choreatic movements, behavioral and psychiatric disturbances and dementia. "Three of these were downregulated in Huntington’s disease compared with WT mice under SH conditions (MAST3, PRKCB and CAMK4) and could therefore be responsible for changes in the phosphoproteome observed between these two groups." (PMID 36523271, 2022).
microcephaly (1 paper, 2021). A congenital or acquired developmental disorder in which the circumference of the head is smaller than normal for the person's age and sex. "In addition, human patients carrying MAST3 missense mutations demonstrates various phenotypes, such as macrocephaly and microcephaly, which may indicate the pathological complexity." (PMID 35095415, 2021).
Rett syndrome (1 paper, 2021). A severe neurodevelopmental disorder affecting the central nervous system. "De novo variants in STK domain of MAST3 gene has been reported to be candidate variants for Rett syndrome-like phenotypes and associated with DEE recently." (PMID 35095415, 2021).
sleep-disordered breathing (1 paper, 2025). "This study is the inaugural investigation to associate MAST3 with OSA, thus paving the way for additional research into the gene’s involvement in sleep-disordered breathing." (PMID 41479897, 2025).
systemic lupus erythematosus (1 paper, 2023). An autoimmune multi-organ disease typically associated with vasculopathy and autoantibody production. "Among these genes, POMC produces peptides involved in anti-inflammatory actions, BANK1 is associated with systemic lupus erythematosus, and MAST3 and AHSA2 are associated with IBD, corroborating the role of immunity-related genes in shaping gut microbiota." (PMID 37081571, 2023).
cancer (1 paper, 2022). A tumor composed of atypical neoplastic, often pleomorphic cells that invade other tissues. "In addition, ARID1A and MAST3 that were located within the branches of patient 14 are among the recurrently mutated cancer genes." (PMID 35379887, 2022).
MAST3 also shares sentences with these, for which no sentence is quoted: Astrocytoma (1 paper); colorectal cancer (1); developmental and epileptic encephalopathy (1); gastric cancer (1); glioblastoma (1); Insulin resistance (1); leukemia (1); melanoma (1); tumor (1).